KDM6A (lysine demethylase 6A)
Diseases named in the same sentence as KDM6A in open-access papers (continued):
Sharing a sentence is not in itself a finding about the gene and the disease.
cervical carcinoma (9 papers, 2013 to 2024). A carcinoma arising from either the exocervical squamous epithelium or the endocervical glandular epithelium. "Cervical cancer cells have been demonstrated to be addicted to KDM6A: it is thought that loss of H3K27 trimethylation due to KDM6A activity promotes p21CIP1 expression, which is required to survive E7-induced replication stress." (PMID 33427604, 2021). "Moreover, FACS analysis of SiHa cervical cancer cells showed a significant 17.6% (P = 0.0003) increase in cells with a sub G0/G1 DNA content, supporting the notion that KDM6A depletion in SiHa cells causes apoptotic cell death." (PMID 28968467, 2017). "Moreover, FACS analysis of SiHa cervical cancer cells showed a significant 7.12% (P = 0.0012) increase in cells with a sub G0/G1 DNA content, supporting the notion that KDM6A depletion in SiHa cells causes apoptotic cell death." (PMID 28968467, 2017). "Thus, KDM6A levels are generally higher in cervical cancer cells and cells expressing high-risk HPV E7 than in normal epithelial cells or cells expressing low-risk HPV E7 proteins." (PMID 28968467, 2017). "To address this issue, we first investigated whether ectopic KDM6B expression may rescue the loss of viability caused by KDM6A depletion in CaSki cervical cancer cells." (PMID 28968467, 2017). "To reinforce the clinical implications of our findings, we obtained cervical cancer samples to confirm the expression of UTX (KDM6A) and JMJD3 (KDM6B)." (PMID 38576048, 2024). "These analyses suggest that KDM6A, KDM6B, and RRM2 help cervical cancer cells tolerate HPV E7-associated replication stress independently of TLS gene expression, highlighting the substantial investment that cells commit to mitigating this stress." (PMID 36266721, 2022). "We have previously reported that depletion of KDM6A in the HPV16-positive cervical cancer line CaSki markedly inhibited cell viability." (PMID 28968467, 2017). "KDM6A expression is necessary for survival of high-risk HPV E7 expressing cells, including several cervical cancer lines." (PMID 28968467, 2017). "Knockdown of either KDM6A or KDM6B in HPV+ cervical carcinoma cell lines not only reduced p16 expression, but also induced cell death." (PMID 29069809, 2017). "Given the result that KDM6A as well as KDM6B expression is essential for viability to cervical carcinoma cells, KDM6 inhibition should be evaluated as a therapeutic modality for some human cancers." (PMID 23673719, 2013). "Since E6 does not markedly modulate sensitivity to KDM6A depletion, and given that E6 and E7 are the only HPV proteins consistently expressed in cervical carcinoma lines, these results show that KDM6A addiction of cervical carcinoma cells arises as a consequence of E7 expression." (PMID 28968467, 2017). "We next assessed KDM6A levels in several cervical cancer cell lines." (PMID 28968467, 2017). "To determine whether KDM6A and/or p21CIP1 induction by E7 affected the incidence of DNA double strand breaks, we evaluated the number of 53BP1 nuclear bodies in KDM6A and p21CIP1 depleted SiHa cervical cancer cells." (PMID 28968467, 2017). "By this definition, cervical carcinoma cells are addicted to KDM6A expression." (PMID 28968467, 2017). "In addition to cell viability assays, we also determined cell numbers by Sulforhodamine B (SRB) assays following infection of SiHa cervical carcinoma cells with the recombinant KDM6A shRNA 60 expressing lentivirus at ten days after puromycin selection." (PMID 28968467, 2017). "Since many cervical carcinoma lines remain KDM6A and p21CIP1 addicted, this suggests that this pathway may be targetable for therapeutic intervention." (PMID 28968467, 2017). "Ectopic p21CIP1 expression rescued the decrease in viability of KDM6A depleted CaSki cervical cancer cells (P < 0.0001, KDM6A depletion compared to KDM6A depletion plus p21CIP1 expression) and HPV16 E7 expressing HFKs (P < 0.0001, KDM6A depletion compared to KDM6A depletion plus p21CIP1 expression)." (PMID 28968467, 2017).
cervical carcinoma (continued). "Hence, it was surprising that KDM6A as well as KDM6B depletion dramatically inhibited viability of the HPV16 positive CaSki cervical carcinoma line." (PMID 23673719, 2013). "To further analyze the hypothesis that KDM6A and p21CIP1 addiction is based on the role of p21CIP1 in dampening replication stress in E7 expressing cells, we analyzed replication in individual DNA fibers in KDM6A and p21CIP1 depleted SiHa cervical cancer cells." (PMID 28968467, 2017). "Our analysis of primary human tumors indicates that KDM6A expression is significantly increased in HPV+ head and neck and cervical carcinoma cells with respect to HPV- tumors and likely normal control tissue." (PMID 29069809, 2017). "KDM6A levels were higher than in primary human foreskin keratinocytes in the HPV16-positive SiHa and CaSki, the HPV18-positive HeLa, and the HPV39-positive Me-180 cervical cancer cell lines." (PMID 28968467, 2017).
diabetic nephropathy (9 papers, 2019 to 2025). "Pathogenic conditions associated with aberrant expression of KDM6A, ANXA11 and SH3YL1 include pediatric cancer, ALS and diabetic nephropathy, respectively." (PMID 37026480, 2023). "GSK-J4 is a specific dual antagonist against histone lysine demethylase 6A/6B (KDM6A/6B) and was reported to be effective in treating diabetic nephropathy." (PMID 35722096, 2022). "Another functional study in HK-2 kidney cells examining the role of hsa-miR-199a-3p in diabetic nephropathy showed that hsa-miR-199a-3p protects these cells from diabetic-induced injury by upregulating E-cadherin expression through the repression of KDM6A, a histone lysine demethylase." (PMID 40904799, 2025). "Interestingly, several reports have shown that KDM6A plays a novel regulatory role in diabetic kidney disease." (PMID 34257820, 2021). "Fourth, elevated levels of KDM6A protein or mRNA could be also observed in kidney tissues or in urinary exosomes of human diabetic nephropathy patients as compared to controls." (PMID 30948420, 2019). "Consistent with the notion, we also show that levels of both KDM6A and KLF10 proteins or mRNAs are substantially elevated in kidney tissues or in urinary exosomes of human diabetic nephropathy patients as compared with control subjects." (PMID 30948420, 2019). "Moreover, to further confirm our study findings, we attempted to examine levels of KDM6A, KLF10, and nephrin mRNAs in urinary exosomes of control subjects and patients with diabetic nephropathy (n = 12 for each group)." (PMID 30948420, 2019). "Quantitative analysis of mRNA contents in human urinary exosomes also showed that higher levels of exosomal KDM6A and KLF10 mRNAs, accompanied by lower levels of nephrin mRNA, were significantly observed in diabetic nephropathy subjects than in control subjects." (PMID 30948420, 2019).
lymphoma (9 papers, 2018 to 2024). A malignant (clonal) proliferation of B- lymphocytes or T- lymphocytes which involves the lymph nodes, bone marrow and/or extranodal sites. "Dependent on expression dosage, KDM6A deficiency was found to accelerate and promote cancer progression in a mouse lymphoma model." (PMID 31201358, 2020).
Kabuki syndrome 2 (8 papers, 2022 to 2025). "Interestingly, the GO terms bone development (e.g. Has2) and hard palate development (e.g. Cbfb) are also highlighted, consistent with high-arched palate and other distinctive bone and facial features observed in Kabuki type 2 syndrome caused by KDM6A mutations in human." (PMID 35871105, 2022). "Lysine demethylase 6A, (KDM6A, MIM*300128) is the pathogenic gene of Kabuki syndrome type 2 (KS2, MIM#300867), which accounts for only 5%–8% of KS." (PMID 38373926, 2024).
melanoma (8 papers, 2016 to 2025). A malignant, usually aggressive tumor composed of atypical, neoplastic melanocytes. "To determine if particular immune subsets are associated with KDM6A in melanoma, we compared the expression of the markers in females versus males in the TCGA data." (PMID 32731355, 2020). "Kaplan–Meier analysis showed that the high KDM6A mRNA expression was associated with better overall survival in the skin cutaneous melanoma (SKCM) melanoma cohorts (p < 0.05)." (PMID 32731355, 2020). "It was of great interest to find that there was a much stronger association of KDM6A expression with TILs in melanoma in female compared to male patients." (PMID 32731355, 2020). "Our application of these findings to melanoma patients in the TCGA database appears to make a strong case for the involvement of two of these X-linked epigenetic regulators (KDM6A and ATRX) in this improved survival." (PMID 32731355, 2020). "Tumoral KDM6A was expressed at higher levels in females and was associated with inferred lymphoid infiltration into melanoma." (PMID 32731355, 2020). "Additional roles in immune responses against cancer have been revealed for KDM5C and KDM6A in survival studies on human melanoma patients and may be linked to higher expression from X linked chromosomes." (PMID 34220955, 2021). "This suggested that the level of EZH2 and its demethylase KDM6A may play a pivotal role in regulating genes associated with immune evasion in melanoma." (PMID 32731355, 2020). "Notably, higher expression of DDX3X and KDM6A was associated with better melanoma-specific survival in all patients (only when analyzed on a continuous scale for the former)." (PMID 32731355, 2020). "Collectively these studies show that EZH2 has an important role in the progression of melanoma, therefore its only known antagonist, KDM6A/B, is likely to be of equal importance and warrants exploration." (PMID 34220955, 2021). "Analysis of data in the TCGA on 458 melanoma patients revealed that KDM6A expression was strongly related to improved survival from melanoma in female patients." (PMID 33469152, 2021). "Our recent study showed that KDM6A had a significant prognostic effect in female melanoma patients inducing better overall survival." (PMID 34220955, 2021). "KDM5C and KDM6A have been previously shown to be preferentially expressed in primary melanoma in female patients and that the low levels of tumoral ATRX are associated with the progression of melanoma." (PMID 32731355, 2020). "Not only KDM6A and ATRX were significantly associated with better overall survival, but KDM6A was also particularly higher in female compared to male melanoma patients." (PMID 32731355, 2020). "We also examined the association of age with the high KDM6A and low EZH2 group since it has been reported that the improved survival of female melanoma patients only applies to those below 60 years of age." (PMID 32731355, 2020). "This was consistent with the preferential survival advantage in female melanoma patients with high KDM6A levels." (PMID 32731355, 2020). "The main role of KDM6A/B may be as an antagonist of EZH2 which has been implicated in the growth and progression in melanoma." (PMID 34220955, 2021). "It is also unclear what role the COMPASS complex which contains KDM6A may have in melanoma progression." (PMID 34220955, 2021). "The six pan-cancer X-linked genes (ATRX, CNKSR2, DDX3X, KDM5C, KDM6A, and MAGEC3) were examined for their association with melanoma survival by comparing the survival of all patients with the expression of genes above (high) or below (low) median expression levels." (PMID 32731355, 2020). "In looking for an explanation for these findings, we first examined whether KDM6A might be related to immune responses to melanoma, particularly as the initial analysis of the TCGA data had shown that TILs were the main factor related to the survival." (PMID 32731355, 2020).
melanoma (continued). "This role for ATRX could presumably account for the upregulation of EZH2 target genes in melanoma and the increased expression of the X chromosome-related genes, such as KDM6A." (PMID 32731355, 2020). "Our TCGA gene set enrichment analysis (GSEA) suggests that high KDM6A level associated with upregulation of several immune related pathways like IFN-gamma which may help anti-tumor immunity and survival advantage in female melanoma patients compared to male." (PMID 34220955, 2021). "We found that the glucose deprivation concentration-dependently increased Ser829 phosphorylation of KDM6A in squamous cancer cells HN6 and CAL27, as well as the B16 melanoma cell and HepG2 hepatocellular carcinoma cell." (PMID 41184251, 2025). "Three of these genes—KDM5C, KDM6A, and ATRX—are well-known epigenetic regulators with known tumor-suppressive functions in melanoma." (PMID 32731355, 2020). "The results provided strong evidence for the importance of KDM6A and EZH2 in the improved survival of females from melanoma." (PMID 32731355, 2020). "The melanoma-specific survival (MSS) in the LMC data also showed a weak increase in survival in patients with high KDM6A and low ATRX levels compared to that in patients with low levels of both KDM6A and ATRX." (PMID 32731355, 2020).
prostate carcinoma (8 papers, 2018 to 2023). A carcinoma that arises from epithelial cells of the prostate gland. "Overexpression of KDM6A/B and a reduction in the global levels of H3K27me2/3 were reported in prostate cancer and strongly correlate with disease aggressiveness." (PMID 35915507, 2022). "GSK-J4 targeting KDM6A is an effective therapeutic strategy against craniosynostosis, lymphoblastic and myeloid leukemias, and breast, ovarian and prostate cancers." (PMID 35185915, 2022). "One study suggested that KDM6A was up-regulated in prostate cancer." (PMID 36797239, 2023). "Inhibition of KDM6A/B with GSK-J4 has been shown to inhibit the proliferation of prostate cancer cell lines with castration-resistant prostate cancer cell lines, specifically those lacking the androgen receptor, exhibiting the highest sensitivity." (PMID 35915507, 2022).
T-cell acute lymphoblastic leukemia (8 papers, 2015 to 2024). Acute lymphoblastic leukemia of T-cell origin. "Two patients harbored mutations in KDM6A, both with a diagnosis of T-cell ALL but only one patient had CR." (PMID 35008312, 2021). "In this regard, opposite functions of KDM6B and KDM6A have been demonstrated in the T-cell acute lymphoblastic leukaemia (T-ALL), being KDM6B essential to initiate and maintain these tumors, whereas KDM6A acts as a tumour suppressor, being frequently genetically inactivated." (PMID 26580594, 2015).
chronic myelomonocytic leukemia (7 papers, 2016 to 2025). A myelodysplastic/myeloproliferative neoplasm which is characterized by persistent monocytosis, absence of a Philadelphia chromosome and BCR/ABL fusion gene, fewer than 20 percent blasts in the bone marrow and blood, myelodysplasia, and absence of PDGFRA or PDGFRB rearrangement. "Deficiency of KDM6A induces myeloid lineage skewing and drives the development of a chronic myelomonocytic leukemia (CMML)‐like disease." (PMID 40365824, 2025).
hyperinsulinism (7 papers, 2020 to 2025). Abnormally high levels of insulin in the blood. "A congenital hyperinsulinemia hypoglycemia revealed heterozygous truncating variant in the KDM6A gene, also known as X‐linked Kabuki syndrome in a newborn." (PMID 37257167, 2023). "More recently, the KDM6A Xp11.3 gene (also known as UTX) has been associated with hyperinsulinism and hearing loss." (PMID 34821691, 2021). "However, more insidious symptoms can rarely occur, such as manifestations of hypoglycemia in newborns with congenital hyperinsulinism hypoglycemia, especially when a variant of the KDM6A gene is found." (PMID 37257167, 2023).
pancreatic ductal adenocarcinoma (7 papers, 2017 to 2025). An infiltrating adenocarcinoma that arises from the epithelial cells of the pancreas. "Notably, lysine (K)-specific demethylase 6A (KDM6A), a frequently mutated tumor suppressor gene in pancreatic ductal adenocarcinoma (PDAC), has been implicated in NET regulation." (PMID 40365275, 2025). "The locus encoding the transcription factor HNF1A harbors susceptibility variants for pancreatic ductal adenocarcinoma (PDAC), while KDM6A, encoding Lysine‐specific demethylase 6A, carries somatic mutations in PDAC." (PMID 32154941, 2020). "Moreover, we examined the expression status of KDM6A in a unique patient cohort comprising matched high-grade PanIN and pancreatic ductal adenocarcinomas (PDAC) of the same patient." (PMID 34509979, 2022).
renal cell carcinoma (7 papers, 2012 to 2026). "Emerging evidence has found that histone demethylases (KDMs), the key regulators in histone modifications, such as KDM3A, KDM5C, KDM6A, and KDM6B, can promote renal cell carcinoma (RCC) progression via hypoxia-mediated angiogenesis pathways." (PMID 32092824, 2020). "Similarly, sex differences in KDM6A expression implicating KDM6A upregulation in renal cell carcinoma have not been described in the literature." (PMID 37655466, 2023).
Autoimmunity (6 papers, 2020 to 2023). The occurrence of an immune reaction against the organism's own cells or tissues. "Kdm6a has been implicated in the risk of acquiring autoimmunity and reported to regulate multiple immune response genes." (PMID 33849979, 2021). "Strong evidence has emerged for Kdm6a and Kdm5c (Lysine-specific demethylase 6a and 5c), two X-linked genes and Uty/Kdm6c (Lysine-specific demethylase 6c), a Y-linked gene, as candidates for contributing to sex differences in mouse models of cancer, autoimmunity, metabolic disease and Alzheimer's." (PMID 34124200, 2021). "Considering the known association of autoimmunity to allograft rejection, this may explain the positive enrichment of ALLOGRAFT REJECTION in the KDM6A high group." (PMID 32731355, 2020). "Mutation in KDM6A has not previously been described as mediating the non-T cell-inflamed phenotype however KDM6A is a known epigenetic regulator of interleukin-6 and IFN-β and linked to autoimmunity." (PMID 33106165, 2020). "Should metformin be found to increase the levels of KDM6A/global H3K27me3 levels in females with a nerve injury, the outcome may not be favorable, given the link between KDM6A and autoimmunity." (PMID 33183347, 2020).
colon cancer (6 papers, 2017 to 2026). "This may provide insights into why colon cancer is more prevalent in men than in women, since KDM6A is an X-chromosome-associated gene." (PMID 40659611, 2025). "Our findings revealed that colon cancer cells co-cultured with KDM6A-depleted fibroblasts formed more colonies than those co-cultured with NAFs." (PMID 40659611, 2025). "This is also supported by the recent observation that KDM6A is necessary for H3K27me3 demethylation at the CDH1 locus in colon cancer cells." (PMID 29029452, 2017). "Next, we assessed the role of KDM6A depletion in fibroblasts on colon cancer formation." (PMID 40659611, 2025). "In a colon cancer model induced by AOM (azoxymethane)/DSS (dextran sulfate sodium), the KDM6A/B-specific inhibitor GSK-J4 markedly reduced the number of tumors (13 per mouse) compared to the inactive GSK.J2 (22 per mouse)." (PMID 40659611, 2025).